MTOR (mechanistic target of rapamycin kinase)
Diseases named in the same sentence as MTOR in open-access papers (continued):
Sharing a sentence is not in itself a finding about the gene and the disease.
breast cancer (continued). "While there is some clinical evidence of activity of mTOR inhibition in HR-positive and HER2-positive breast cancers, the benefits may be more pronounced in selected subsets rather than in the overall population." (PMID 26779371, 2015). "Then, we further examined mTOR mitochondrial location and cellular bioenergetics in paired normal and cancer cells, including normal human breast epithelial cells MCF-10A and breast cancer MCF-7 cells; and human prostate epithelial cells 267B1 and their K-Ras transfected derivative, 267B1/Ki." (PMID 25807077, 2015). "In this regard, it is important to note that the same AKT gene module that correlates with poor outcome in endocrine-treated ER+ breast cancer, was also able to predict a high activity score in breast cancer cell lines that were particularly sensitive to treatment with PI3K/AKT/mTOR inhibitors." (PMID 25886003, 2015). "First, insulin is a well-known growth factor, which may activate the proliferation of breast cancer cells through its interaction with the insulin receptor or the IGF-1 receptor and through activating the mTOR pathway." (PMID 26537234, 2015). "Furthermore, in other breast cancer cell lines (HBL100, MDA-MB-231 and HCC1937), PP242 and mTOR siRNA treatment in HBL100 cells inhibited all three Chk1 phosphorylations induced by etoposide." (PMID 25460505, 2015). "In human breast cancer cells, AA effectively activates both mTOR complexes and its effect is mediated by lipoxygenase but not cicloxygenase metabolites." (PMID 26536660, 2015). "The signaling response of concurrent targeting of both PI3K and mTOR pathways, as measured by phosphorylation of AKT and p70S6K respectively, did not predict growth inhibitory effects in MDA-MB-231, MDA-MB-436, BT20 and HCC1143 breast cancer cell lines." (PMID 26148118, 2015). "Using the same AKT gene module as before, we estimated activity scores for 39 breast cancer cell lines (Affymetrix gene expression data), which were then correlated to − log10IC50 values for 140 drugs, including rapamycin and 10 other AKT/PI3K/mTOR inhibitors." (PMID 25886003, 2015). "Activation of the Akt signaling pathway upon mTOR inhibition via a negative feedback loop has been observed in many cell types, including breast cancer cell lines." (PMID 26132202, 2015). "We have also investigated whether the dual PI3K/mTOR inhibitors BEZ235 and GSK2126458, or the dual mTORC1/mTORC2 inhibitor (AZD8055), can sensitize everolimus resistant breast cancer cell lines to everolimus by reducing AKT phosphorylation." (PMID 26148118, 2015). "From all this, we can conclude that DART-CLQ was instrumental in identifying a specific AKT gene module (derived from the METABRIC discovery set), which can simultaneously predict tamoxifen resistance in ER+ breast cancer patients and sensitivity to PI3K/AKT/mTOR signaling inhibitors." (PMID 25886003, 2015). "Importantly, this resistance was overcome by the inhibition of mTOR activity with PP242, which significantly decreased breast cancer cell viability following DNA damage." (PMID 25460505, 2015). "We found that the mTOR inhibitor rapamycin inhibited the transcriptional activation of the FASN promoter and FASN mRNA expression in breast cancer cells, especially in ER+/HER2+ breast cancer cells." (PMID 24866893, 2014). "Lapatinib has been shown to inhibit the HER2 downstream signaling pathways RAF/MEK/ERK (ERK cascade) and PI3K/AKT/mTOR and lead to up-regulations of BIM (BCL-2–interacting mediator of cell death) and BID (BCL-2 antagonist of cell death) in HER2-overexpressed breast cancer cells." (PMID 24947902, 2014). "The addition of mTOR inhibitor everolimus (EVE) to exemestane (EXE) was evaluated in an international, phase 3 study (BOLERO-2) in patients with hormone-receptor-positive (HR+) breast cancer refractory to letrozole or anastrozole." (PMID 23404211, 2014).
breast cancer (continued). "Consistently, in our experimental conditions addition of 10 nM OHPg reduced the cellular content of pAKT and total AKT and its downstream target mTOR either in basal conditions or following treatment with IGF-1, a relevant factor in breast cancer growth and progression." (PMID 25216078, 2014). "Furthermore, the activated mTOR pathway promoted FASN expression, which results in the malignant phenotype transformation of breast cancer cells." (PMID 24866893, 2014). "Additional studies showed that +SA mammary tumors grown in syngeneic mice also displayed elevated HIF-1a levels and enhanced Akt/mTOR, p70S6K, and eIF-4E1 activation, and treatment with compound 44, but not its parent compound, δ-tocotrienol, blocked this compensatory response to hypoxic conditions." (PMID 25140303, 2014). "There was no observed correlation for mTOR expression with either an ERα+ or ERα− breast cancer phenotype." (PMID 25283550, 2014). "Subsequently, several MTOR inhibitors have been evaluated for the treatment of various cancers in phase III clinical trials, including Non-Hodgkin lymphoma, neuroendocrine tumors, gastric cancer, sarcoma, hepatocellular carcinoma, breast cancer, and etc.." (PMID 25375091, 2014). "In breast cancer, ERα/mTOR crosstalk is an important indicator of hormone receptor status, as IGF-mediated mTORC1 activation repressed progesterone receptor (PgR) expression in the ER+/PgR− breast cancer cell phenotype." (PMID 25283550, 2014). "Therefore, the relationship of mTOR and p-S2448 mTOR to clinical outcome defined by RFS (RFS = endpoint recurrence and/or death due to BC) and OS from death due to breast cancer (OS = endpoint death due to breast cancer) was determined." (PMID 24887419, 2014). "Considering that PC-derived second messengers are involved in the activation of cellular signaling mediators like mTOR and MAPKs, activation of the Akt-mTOR and MEK1/2-ERK1/2 signaling pathways by phosphatidylcholine was analyzed in the MCF-7 breast cancer cell line." (PMID 24772432, 2014). "In the present study, the expression levels of phosphorylated (p)-mTOR and p-4E-BP1 were analyzed in breast cancer patients prior to and following NAC, to determine whether p-mTOR and p-4E-BP1 affect the response to NAC and the subsequent survival." (PMID 25364442, 2014). "This hypothesis is supported by data in breast cancer, which show little predictive value of PIK3CA with the mTOR inhibitor everolimus." (PMID 24777052, 2014). "The higher mTOR phosphorylation in the metastasis-derived cell line (FMCm) compared with its primary counterpart (FMCp) suggests a significant involvement of p-mTOR in metastasis, invasion and FMC tumor progression, such as in human breast cancer." (PMID 23587222, 2013). "The mammalian target of rapamycin (mTOR) pathway may be activated by PI3K/Akt signaling, as well as by AA, to alter lipid metabolism and stimulate anabolic growth in breast cancer cells." (PMID 24070020, 2013). "The outcomes of this study illustrated that Girdin and PI3K have a linear correlation in breast cancer and they may be necessary to the PI3K/Akt/mTOR pathway." (PMID 23760650, 2013). "According to the authors, the greatest advantage of targeting the IGF system is its crosstalk with other signalling pathways, as preclinical work has identified significant antitumor activity when IGF-1R is concordantly targeted with mTOR, ERα, the EGF receptor and HER2 in breast cancer." (PMID 23483937, 2013). "The authors correlated these results with an analysis of pathway activation in breast cancer patients who had progressed on letrozole, finding an upregulation of PI3KA, pAkt and p-mTOR after three months on treatment in comparison to the patients' pre-treatment baseline." (PMID 23880059, 2013). "More recently, others have shown that breast cancer cell lines with PTEN loss of function, were not sensitive to second generation mTOR inhibitors, specifically PP242." (PMID 23451056, 2013).
breast cancer (continued). "Experimental Design: To test our hypothesis we assessed the inhibitory effect of protein diet restriction on prostate and breast cancer growth, serum PSA and IGF-1 concentrations, mTOR activity and epigenetic markers, by using human xenograft cancer models." (PMID 24353195, 2013). "In vitro and xenograft models of breast cancer have also demonstrated that cells harboring amplification of the RTK HER2 are dependent on PI3K pathway activation and sensitive to its inhibition through targeting of PI3K, dual PI3K/mTOR, AKT, and mTOR kinase." (PMID 22970424, 2012). "In human breast cancer cells, it reduces HER-2 protein expression by inhibiting mTOR." (PMID 22448244, 2012). "The PI3K/PTEN/Akt/mTOR and Raf/MEK/ERK pathways differed in their abilities to modulate the induction of cellular senescence in response to doxorubicin treatment in breast cancer cells as activated Akt-1 impeded senescence while activated Raf-1 did not, similar to the results of the present study." (PMID 21881167, 2011). "As such, metformin inhibits the mTOR-signaling pathway in an AMPK-dependent manner, which may provide an explanation of the observed anti-neoplastic actions in breast cancer." (PMID 22203527, 2011). "To investigate the molecular changes in HER2 overexpressing breast cancer cells after treatment with the gefitinib and RAD001 combination, we analyzed the expression and phosphorylation of proteins relevant to EGFR, HER2 and mTOR signaling." (PMID 21961653, 2011). "The mTOR inhibitors rapamycin and rapamycin analogues (CCI-779, RAD001, and AP23573) have exhibited impressive growth inhibitory effects against a broad range of human cancers, including breast cancer, in preclinical and early clinical studies." (PMID 21119656, 2011). "This was an application of Akt-mTOR signature derived from a mouse model of Akt activation in prostate to human breast cancer showing that the genes were not tissue or model specific." (PMID 19778445, 2009). "In summary, we found that Pin1-inhibition sensitized Her2-positive breast cancer cells to the mTOR-inhibitor Rapamycin, but not to the direct erbB2 inhibitor Trastuzumab." (PMID 19077306, 2008). "While Pin1-inhibition greatly increased the sensitivity of Her2-positive breast cancer cells to the mTOR inhibitor Rapamycin, it did not increase their sensitivity to Trastuzumab." (PMID 19077306, 2008). "Also Connectivity Map gave the highest scores for Ly294002 and rapamycin in the breast cancer cell lines treated with these inhibitors further validating the gene expression profiles responsive to these PI3K and mTOR inhibitors." (PMID 18652687, 2008). "The authors reported that MDA-MB-231 cells have high-PLD1 activity, which is responsible for promoting mTOR-dependent survival signals in these breast cancer cells that do not express active PI3K/Akt survival signals." (PMID 17726467, 2007). "In this study, we report that PLD1 and phospho-mTOR are coexpressed in a subset of phospho-Akt-negative breast carcinomas." (PMID 17726467, 2007). "In this study, we are the first to demonstrate that the PLD1/mTOR pathway is active in a subset of clinical breast carcinomas that are negative for phospho-Akt." (PMID 17726467, 2007). "The mammalian target of rapamycin (mTOR; also known as FRAP, RAFT1 and RAPT1) is a downstream effector of the PI3/Akt pathway that has recently received great attention as a potential novel therapeutic modality for the treatment of breast cancer." (PMID 16859513, 2006). "Although EGFR was suggested to be one of upstream regulators of PDK-1/AKT and Stat3 pathways, the role of EGFR activation plays in relation to PDK-1/AKT/mTOR/p70S6K/S6 cascade in breast cancers has not been firmly established." (PMID 16288304, 2005). "Elevated phosphorylation of PDK-1, mTOR and increased AKT kinase activity in both MDA-MB-468 and MCF-7 breast cancer cell lines indicated that they may play important roles in breast carcinogenesis." (PMID 16288304, 2005).
breast cancer (continued). "In addition, by encouraging the breakdown of hypoxia-inducible factor 1α(HIF-1α) protein and preventing the stimulation of the PI-3 K/Akt/mTOR/HIF-1α/VEGF axis, dauricine reduces the creation of HIF-1α protein, which in turn prevents angiogenesis in human breast cancer cell lines." (PMID 40205002, 2025). "In breast cancer tissues, a significant downregulation of SASH1 expression has been observed, whereas upregulation of SASH1 is able to block the proliferation and invasion of breast cancer cells through inhibition of the PI3K-Akt-mTOR (mammalian target of rapamycin) signaling route." (PMID 39942820, 2025). "Quercetin has the capability to influence multiple signaling pathways, including the PI3K/Akt/mTOR and MAPK/ERK1/2 pathways, as documented in prior research, Moreover, it has demonstrated anti-tumor properties in various cancer types, such as ovarian cancer, esophageal cancer, and breast cancer." (PMID 40575382, 2025). "Furthermore, UA has demonstrated the capacity to potentiate adriamycin’s anti-tumor effects by inhibiting proliferation and migration of breast cancer (MDA-MB-231/DOX and MCF-7/ADR) cells, as well as by inducing mitochondrial dysfunction via the AMPK/mTOR/PGC-1α signaling pathway [1047]." (PMID 40490812, 2025). "The PI3K/AKT/mTOR signaling axis was chosen for investigation in this study due to its well-recognized role in regulating cell proliferation, survival, and therapy resistance in cancer, particularly in aggressive breast cancer subtypes, such as TNBC and HER2+ breast cancer." (PMID 41141380, 2025). "Currently, single node inhibitors (SNIs) of the PI3K/AKT/mTOR pathway alpelisib and inavolisib (targeting PI3Kα) and capivasertib (targeting AKT) have received regulatory approval for breast cancer treatment, while everolimus (mTORC1 inhibitor) is approved for breast cancer and other tumour types." (PMID 40360883, 2025). "In ER + breast cancer, the interplay between PI3K-Akt-mTOR pathway and estrogen receptor α pathway drives resistance to endocrine therapy, suggesting that combination therapy with tamoxifen and empagliflozin could prevent or overcome resistance to anti-hormonal therapy." (PMID 39066911, 2025). "Several studies have shown an increased breast cancer specific mortality in patients with metabolic syndrome, likely due to crosstalk between the insulin-like growth factor (IGF) family and signaling pathways that drive tumorigenesis, including the PI3K/AKT/mTOR pathway." (PMID 41157306, 2025). "In spontaneous mouse models of breast cancer, enhanced SLC6A14 expression promotes the growth of ER-positive breast tumors, while SLC6A14 gene knockout mice exhibit breast tumors with amino acid starvation, weakened mTOR signaling, and reduced cell proliferation." (PMID 39973065, 2025). "In addition, combination strategies for novel PAM pathway inhibitors, including the novel PI3K—mTOR dual inhibitor gedatolisib, AKT inhibitor NTQ1062, mTOR inhibitor sapanisertib and vistusertib, are also being developed and explored in breast cancer." (PMID 40206206, 2025). "Obesity may also influence breast cancer development through various other mechanisms, including activation of the PI3K/Akt/mTOR signaling pathway, upregulation of leptin, downregulation of adiponectin, increased insulin-like growth factor signaling, and elevated proinflammatory cytokine production." (PMID 41227211, 2025). "Based on this preclinical and clinical data, we hypothesized that combination therapy with a dual mTOR/pan-PI3 K inhibitor, gedatolisib, and the PARPi, talazoparib, may be effective in breast cancer patients with a gBRCA1/2 m and in patients with BRCA1/2-wildtype TNBC." (PMID 40471518, 2025). "Additionally, combinations of neratinib with multi-kinase inhibitors like dasatinib or with downstream signaling inhibitors, such as mTOR and CDK4/6 inhibitors, have demonstrated strong preclinical efficacy by suppressing key survival pathways in HER2-positive breast cancer models." (PMID 39684551, 2024).
breast cancer (continued). "Pimozide might promote autophagy in breast cancer cells by up-regulating cAMP, rather than by inhibiting mTOR signaling." (PMID 38356266, 2024). "Second, the authors speculate that oxycodone promotes the antitumor properties of PTX, but the authors did not intervene with the signalling pathway and autophagy to further explore the specific roles of PI3K/Akt/mTOR and autophagy in the effects of OXY and/or PTX on breast cancer cells." (PMID 39084065, 2024). "Collectively, the results of the present study highlighted that Bag‐1 overexpression in HER2+ breast cancer cells, specifically BT‐474 cells, may regulate the expression of HSPs through promoting HSF1 phosphorylation at Ser326, through the PI3K/AKT/mTOR pathway." (PMID 39049197, 2024). "In particular, inhibitors of the PI3K/AKT/mTOR pathway, abnormally activated in many breast cancers, failed to achieve clinical efficacy in TNBC due to the development of adaptive drug resistance, which is largely driven by the transcriptomic plasticity of TNBC." (PMID 39541354, 2024). "The objective of our study is to evaluate whether vitamin D3 conjugated to gold nanoparticles—VD3-GNPs—can reduce breast cancer aggressiveness and alter important cancer cellular pathway proteins (PI3K/AKT/mTOR, ETV7, and YAP/TAZ), so that the VD3-GNPs can be a cancer therapy." (PMID 38791386, 2024). "Endocrine-resistant breast cancer cells promote COX-2 expression in TAMs via the JNK/c-Myc/arginase-1 pathway and further promote endocrine resistance in breast cancer cells by activating the PI3K/Akt/mTOR pathway, forming a positive feedback loop between TAMs and breast cancer cells." (PMID 39199574, 2024). "Inhibition of PI3K/AKT/mTOR induces cell apoptosis and enhances doxorubicin (DOX) efficacy in breast cancer (BC)." (PMID 38671354, 2024). "However, the lack of MARCH1 greatly promote the proliferation of breast cancer cells by enhancing mTOR signaling pathway." (PMID 39061024, 2024). "In this study, we tested the pan-PI3K/mTOR inhibitor, gedatolisib, and node-selective inhibitors for PI3Kα (alpelisib), AKT (capivasertib) and mTORC1 (everolimus) to compare the functional effect of inhibiting single versus multiple PAM pathway nodes in a panel of breast cancer cell lines." (PMID 38839777, 2024). "However, the relationship between physical activity and mTOR activities in the tumors of patients with breast cancer has not been reported." (PMID 36895729, 2023). "Furthermore, immunohistochemistry and immunofluorescence experiments verified that LHX2 promoted the expressions of infiltrating T cells and CD4 + T cells in breast cancer, and a Western blot assay demonstrated that LHX2 activates the PI3K/AKT/mTOR pathway and apoptosis pathway." (PMID 37345110, 2023). "As mTOR suppresses FZD levels on the plasma membrane of intestinal stem cells, it is intriguing to consider whether PI3K/mTOR inhibition may increase FZD surface expression in ER− breast cancer." (PMID 37471270, 2023). "Metformin can inhibit the mTOR pathway by activating AMPK, which may lead to reprogramming of cancer metabolism, which in turn exerts inhibitory effects on cancers such as liver, colorectal and breast cancers." (PMID 37773165, 2023). "Recently, B591 carrying a 2,3-dihydrobenzofuran core and potently inhibiting the PI3 K/mTOR signaling pathway suppresses feedback activation of ERK and Akt in rhabdomyosarcoma RD and breast cancer cells, indicating that B591 might have enhanced anticancer activity." (PMID 36704446, 2023). "Drugs including celecoxib (COX-2 inhibitor) and rapamycin (mTOR inhibitor) were co-loaded into the nanocapsules to inhibit the proliferation of MCF-7 and MDA-MB-231 breast cancer cells, signifying the enhanced cytotoxicity of the nanocapsules against breast cancer cells." (PMID 37346950, 2023).